NOS2 (nitric oxide synthase 2)
Diseases named in the same sentence as NOS2 in open-access papers (continued):
Sharing a sentence is not in itself a finding about the gene and the disease.
head and neck cancer (3 papers, 2019 to 2024). A primary or metastatic malignant neoplasm affecting the head and neck. "Production of nitric oxide (NO) via nitric oxide synthase (NOS2) plays a key role in inflammation-dependent head and neck cancer progression." (PMID 31885577, 2019).
knee osteoarthritis (3 papers, 2019 to 2023). "Our results showed that the increased protein levels of NOS2 in this supraspinal region of animals with knee osteoarthritis were inhibited by the administration of slow-releasing H2S donors." (PMID 31905764, 2019).
leprosy (3 papers, 2015 to 2022). Leprosy is a chronic infectious disease affecting primarily the skin and peripheral nervous system. "Other models such as severe combined immunodeficiency (SCID) mice and mice having gene-knockouts (KO) of IFN-γ and nitric oxide synthase 2 (NOS2) failed to reproduce human leprosy-like regions." (PMID 36326715, 2022).
liver cancer (3 papers, 2021 to 2023). An epithelial or non-epithelial malignant neoplasm that arises from the liver. "It has been reported that the presence of NOS2 in mitochondria of liver cancer cells was associated with more aggressive phenotypes of cancer cells." (PMID 34176789, 2021). "In liver cancer cells, the overexpression of NOS2 and NOS3 induces a transition between apoptosis and autophagy by disrupting the Beclin 1/Vps34 association and increasing the Bcl-2/Beclin 1 interaction." (PMID 37958916, 2023). "Because NOS2 was closely correlated with chronic inflammation and hepatocarcinogenesis in liver cancer." (PMID 34176789, 2021). "Finally, our analysis also revealed the potential of NOS2 as a potential biomarker for diagnosing liver cancer." (PMID 37958916, 2023).
mastitis (3 papers, 2022 to 2025). Inflammation of breast tissue during lactation or postpartum due to an obstructed duct or infection. "1,25(OH)2D3 induces localized expression of NOS2 in milk CD14+ cells and increased CCL5 in CD14- cells during experimentally induced mastitis caused by S. uberis." (PMID 36144467, 2022). "This study aimed to determine the nature of the distribution of the relative frequencies of alleles and genotypes of polymorphic prolactin (PRL) and nitric oxide synthase (NOS2) in Holstein cows and identify the relationship of these genes with resistance to mastitis and bovine leukemia." (PMID 36855359, 2023). "In a similar study, treatment of mammary gland with 25(OH)D3 in cattle with LPS induced mastitis showed total milk somatic cells having upregulated expression of NOS2, RANTES/CCL5, DEFB3, DEFB4, DEFB7, DEFB10, IL1B, and IL8, with most effects being observed between 4–8 h following treatment." (PMID 36144467, 2022). "In a murine acute mastitis model, levels of TNF-α were increased in mammary glands after a lipopolysaccharide challenge, and transcriptome analysis revealed the upregulation of Nos2 and genes involved in the IFN-γ response and TNF-α signaling." (PMID 40564173, 2025). "When cows with subclinical mastitis had their mammary gland treated with 1,25(OH)2D3, upregulation was enhanced further and increased expression was observed for DEFB4 and DEFB7 along with NOS2, with a significant treatment effect being seen by 24 h." (PMID 36144467, 2022).
medulloblastoma (3 papers, 2012 to 2018). A malignant, invasive embryonal neoplasm arising from the cerebellum. "Taken together, these results indicate that Nos2 deficiency promotes medulloblastoma development in Ptch1+/− mice through retention of proliferating GCPs in the external granular layer due to reduced Gap43 expression." (PMID 22438824, 2012). "The increased accumulation of proliferating GCPs in the EGL observed in the Ptch1+/− Nos2−/− genotype supposedly leads to a larger pool of cells susceptible to neoplastic transformation and is therefore likely to promote medulloblastoma development." (PMID 22438824, 2012). "We observed a two-fold higher medulloblastoma rate in Ptch1+/− Nos2−/− mice compared to Ptch1+/− Nos2+/+ mice." (PMID 22438824, 2012). "Ablation of either Nos2 or Tis21 in Shh-activated mice leads to a large increase in the frequency of medulloblastoma." (PMID 23355800, 2012). "Together with the sustained proliferation of these cells in combined Ptch1+/− Nos2−/− mice, this effect results in an increased medulloblastoma incidence relative to Ptch1+/− mice and demonstrates a new disease-promoting mechanism in this tumor entity." (PMID 22438824, 2012). "Finally, this advances medulloblastoma development in Ptch1+/− Nos2−/− mice compared to Ptch1+/− Nos2+/+ mice." (PMID 22438824, 2012).
mental disorder (3 papers, 2018 to 2020). A disease that has its basis in the disruption of mental process. "In our review, we have summarized information regarding all NOS1, NOS2, NOS3, and NOS1AP single nucleotide variants (SNVs) involved in the development of mental disorders and neurological diseases/conditions." (PMID 32111088, 2020). "In our review, we have decided to summarize information regarding all NOS1, NOS2, NOS3, and NOS1AP SNVs involved in the development of mental disorders and neurological diseases/conditions." (PMID 32111088, 2020).
metastatic melanoma (3 papers, 2016 to 2022). A melanoma that has spread from its primary site to another anatomic site. "However, the expression of NOS2 was significantly increased in the vertical growth phase when compared to dysplastic nevus and in metastatic melanoma once compared to the common and dysplastic nevus." (PMID 35326089, 2022).
neuroblastoma (3 papers, 2013 to 2018). Neuroblastoma (NB) is the most common solid, extracranial childhood tumor. "NF-κB has been reported to upregulate the NOS2 gene transcriptionally in hippocampal neurons and in human neuroblastoma cells." (PMID 23880112, 2013).
Oral Squamous Cell Carcinoma (3 papers, 2014 to 2025). "Key words:Field cancerization, oral squamous cell carcinoma, Nitric Oxide Synthase 2 (NOS2), malignity markers." (PMID 24316703, 2014). "Claudin-1 promotes the invasive ability of oral squamous cell carcinoma OSC-4 and NOS-2 cell lines through MT1-MMP and MMP-2 activation." (PMID 35280730, 2022). "The activity of Nitric Oxide Synthase 2 (NOS2) was found in oral squamous cell carcinomas (OSCC) but not in normal mucosa." (PMID 24316703, 2014).
osteomyelitis (3 papers, 2010 to 2024). An acute or chronic inflammation of the bone and its structures due to infection with pyogenic bacteria. "The findings suggest potential linkages between SNPs in genes such as IL-1, IL-6, IFN-γ, TNF-α, VDR, tPA, CTSG, COX-2, MMP1, SLC11A1, Bax, NOS2, and NLRP3 with the development of osteomyelitis." (PMID 39301021, 2024). "Current research has amassed increasing evidence suggesting that SNPs in various genes, including IL-1, IL-6, IFN-γ, TNF-α, VDR, tPA, CTSG, COX-2, MMP1, SLC11A1, Bax, NOS2, and NLRP3, may contribute to the development of osteomyelitis." (PMID 39301021, 2024).
sarcoma (3 papers, 2017 to 2019). A usually aggressive malignant neoplasm of the soft tissue or bone. "Given that L-NAME failed to improve the antitumor efficacy of the anti-PD-1 mAb in Nos2-deficient mice, and that L-NAME had some activity against distinct clones of Ifnar1-deficient sarcomas, we postulate that the functionally relevant source of NO is likely antigen presenting cells." (PMID 31481761, 2019). "Similar to the other sarcomas expression of ARG2 was highest, with modest expression of ARG1 and NOS2 genes." (PMID 28969007, 2017).
toxoplasmosis (3 papers, 2010 to 2024). A parasitic disease contracted by the ingestion or fetal transmission of toxoplasma gondii. "Thus, in spite of upregulation of IFN-γ, TNF-α and NOS2, and the development of T cell-mediated immunity against T. gondii, mice with defective autophagy and with impaired autophagy protein-dependent killing of the parasite are susceptible to toxoplasmosis." (PMID 21217818, 2010). "Susceptibility to toxoplasmosis occurred despite upregulation of IFN-γ, TNF-α and NOS2, preservation of IFN-γ-induced microglia/macrophage anti-T." (PMID 21217818, 2010). "Similar to the studies with Becn1+/− mice, ATG7flox/flox-Lyz-Cre mice were susceptible to toxoplasmosis despite upregulation of IFN-γ, TNF-α and NOS2 mRNA and the generation of T. gondii-specific T cell response." (PMID 21217818, 2010). "Next, we examined whether susceptibility to toxoplasmosis in CD40−/− mice could be explained by impaired expression of IFN-γ, TNF-α and NOS2." (PMID 21217818, 2010). "In addition to IFN-γ, TNF-α, cerebral and ocular mRNA levels of IL-6, NOS2 and IL-10 are increased in the brain and eye of mice infected with T. gondii, and these molecules promote protection against toxoplasmosis while in the case of IL-10, this cytokine modulates susceptibility to disease –." (PMID 23990781, 2013). "Susceptibility to toxoplasmosis was not due to defective expression of IFN-γ, TNF-α, NOS2 or IL-6 in the retina and brain, differences in IL-10 expression in these organs or to impaired induction of T. gondii-reactive T cells." (PMID 23990781, 2013). "This increased susceptibility to toxoplasmosis was not explained by diminished expression of IFN-γ, NOS2 and TNF-α in the brain and eye." (PMID 21217818, 2010).
triple-negative breast carcinoma (3 papers, 2023 to 2026). An invasive breast carcinoma which is negative for expression of estrogen receptor (ER), progesterone receptor (PR), and human epidermal growth factor receptor 2 (HER2). "For instance, miR-939-5p suppresses triple-negative breast cancer progression by inhibiting NOS2 expression." (PMID 37795447, 2023). "Spatial analysis of NOS2, COX2 and CD8 expression in patient tumors has identified mechanisms of treatment inhibition that were further elucidated using the 4T1 mouse model of triple negative breast cancer and live cell culture studies." (PMID 42097035, 2026).
vitiligo (3 papers, 2021 to 2025). Generalized well circumscribed patches of leukoderma that are generally distributed over symmetric body locations and is due to autoimmune destruction of melanocytes. "Our NO data are consistent with reports of UVB-induced NO production in murine PRMφs and human vitiligo skin, but differ from studies where therapeutic UVB inhibited NOS2 expression in keratinocytes and macrophages." (PMID 40895555, 2025).
acute myocarditis (2 papers, 2012 to 2016). The sudden onset of inflammation of heart muscle with myocellular necrosis; this is generally secondary to an infectious cause, and patients often have a recent history of a flu-like illness. "In addition, in rhesus monkeys, the severity of CCC was associated with the intensity of iNOS/NOS2-positive (iNOS/NOS2+) cell-containing myocarditis." (PMID 27161638, 2016). "Nevertheless, iNOS/NOS2-derived NO takes part in ventricular dilation and systolic dysfunction in T. cruzi-elicited acute myocarditis." (PMID 22590660, 2012).
adenoma (2 papers, 2012 to 2020). A neoplasm arising from the epithelium. "Interestingly, miR-17 was commonly altered in adenomas and associated with NOS2 in IBD while miR-181b was altered in adenomas and associated with CD68." (PMID 22970173, 2012).
airway hyperresponsiveness (2 papers, 2006 to 2025). "DiABZI administration during HDM challenge increased airway hyperresponsiveness, neutrophil recruitment with prominent NOS2+ARG1− type 1 neutrophils, protein extravasation, cell death by PANoptosis, NETs formation, extracellular dsDNA release, DNA sensors activation, IFNγ, IL‐6 and CXCL10 release." (PMID 39466641, 2025).
allergic rhinitis (2 papers, 2022 to 2023). Inflammation of the nasal mucous membranes caused by an IgE-mediated response to external allergens. "The SNP genotype distribution of NOS2 gene analyzed in the experiment is very similar to the genetic sequence of allergic rhinitis." (PMID 36845379, 2023).
aortic aneurysm (2 papers, 2017 to 2023). A ruptured aneurysm located in the wall of the proximal portion of the descending aorta proceeding from the arch of the aorta. "Pharmacological inhibition of NOS2 in mice led to a protective effect in aortic aneurysm development." (PMID 28659821, 2017). "Furthermore, the relative mRNA level of inflammatory factors of aortic aneurysm was examined by quantitative PCR, which suggested minoxidil significantly upregulated the expression levels of IFN-γ, NOS2, and CCL2." (PMID 37383707, 2023).
bacteremia (2 papers, 2020 to 2025). "In neonatal meningitis caused by E. coli, NOS2-dependent NO has serious detrimental impact on the outcome of infection, since it promotes development of bacteremia as well as disruption of the blood–brain barrier." (PMID 32459575, 2020).
Bipolar Affective Disorder (2 papers, 2014 to 2020). "In bipolar disorder, protein and mRNA levels of neuroinflammatory markers (IL-1β, IL-1R, MYD88, NF-kB1) and of activated microglia and astroglial markers (GFAP, NOS2, c-Fos, and CD11b) also were significantly higher than in control cortex." (PMID 25329999, 2014).
bronchiolitis (2 papers, 2013 to 2020). Inflammation of the bronchioles characterized by swelling of the bronchioles and mucus accumulation. "The authors observed that the SNP rs2107538*CCL5 was associated with bronchiolitis caused by respiratory syncytial virus (RSV) and RSV-subtype-A while the SNP rs1060826*NOS2 was associated with bronchiolitis caused by rhinovirus, indicating viral-specific polymorphisms." (PMID 32375305, 2020).
Cachexia (2 papers, 2015 to 2021). Severe weight loss, wasting of muscle, loss of appetite, and general debility related to a chronic disease. "Gene expression of Nos2 (Nitric oxide synthase 2), which has previously been described as important regulator of both age-related sarcopenia and cachexia, was significantly decreased by the presence of a tumor in the GC muscle of all models." (PMID 35008253, 2021).
cardiomyopathy (2 papers, 2012 to 2020). A disease of the heart muscle or myocardium proper. "To add insights on the participation of iNOS/NOS2-derived NO in T. cruzi-elicited cardiomyopathy, we studied the effect of the infection of iNOS/NOS2-deficient (Nos2tm1Lau/J) mice in different aspects of heart injury." (PMID 22590660, 2012). "Our findings support that parasite-driven iNOS/NOS2+ cells accumulation in the cardiac tissue and NO overproduction contribute to cardiomyopathy severity, mainly disturbing the pathway involved in electrical synchrony in T. cruzi infection." (PMID 22590660, 2012).
cerebral malaria (2 papers, 2017 to 2019). A sequestration of Plasmodium falciparum in the brain, which can cause coma and/or seizures. "Further research is needed to clarify how HMOX1 gene variants act in cerebral malaria pathogenesis but its tempting to speculate that genetic interaction with NOS2 functional variants may help to explain the contribution of HMOX1 to the genetic complexity of human cerebral malaria." (PMID 31417551, 2019). "This difference between populations is mainly due to a SNP in NOS2, which occurs in the population of African ancestry with higher than average frequency (rs3730017, AFAFR = 19% vs AFglobal = 4%) and while not functionally characterized, has been associated with protection against cerebral malaria." (PMID 29273096, 2017).
cerebral toxoplasmosis (2 papers, 2010 to 2025). Infections of the brain caused by the protozoan toxoplasma gondii that primarily arise in individuals with immunologic deficiency syndromes (see also aids-related opportunistic infections). "Protection against ocular and cerebral toxoplasmosis in Saracatinib-treated mice was not the result of increased local expression of IFN-γ, TNF-α, IL-12 p40, and NOS2, mediators of resistance against ocular and cerebral toxoplasmosis." (PMID 39869638, 2025). "IFN-γ, TNF-α and their downstream effector molecule NOS2 are considered the mediators of resistance against ocular and cerebral toxoplasmosis." (PMID 21217818, 2010). "Thus, CD40−/− mice are susceptible to ocular and cerebral toxoplasmosis despite upregulation of key mediators of host protection: IFN-γ, TNF-α and NOS2." (PMID 21217818, 2010).
childhood asthma (2 papers, 2021 to 2026). "We found a significant epistatic interaction between two variants of NOS2 gene (rs2297518 and rs10459953, 2-locus model) and childhood asthma risk." (PMID 34946286, 2021). "Our study shows an association between rs10459953 in NOS2 gene and childhood asthma, which was the first to explore it in Polish population." (PMID 34946286, 2021).
chronic gastritis (2 papers, 2010 to 2025). Inflammation of the stomach that is chronic in nature. "Distribution of risk factors, genotypes of NOS2 polymorphisms Ser608Leu and -954G/C, and odds ratios (OR) for gastric adenocarcinoma (GA), chronic gastritis (CG), and control (C) groups." (PMID 20565800, 2010). "Genotype and allele frequencies of NOS2 polymorphisms Ser608Leu, -954G/C and -1173C/T in gastric adenocarcinoma (GA), chronic gastritis (CG), and control (C) groups." (PMID 20565800, 2010). "In addition, an increase in NOS2 activity have been observed in chronic gastritis with IM." (PMID 39897791, 2025).
colorectal tumor (2 papers, 2017 to 2018). "Having demonstrated the link between TLR4/NF-κB and TNF-α/NOS2 induction in colorectal tumors, we focused our attention to elucidate the immunomodulatory effect of all-trans retinoic acid in NOS2 and TNF-α expression in inflamed colonic mucosa cultures." (PMID 28408791, 2017).
dengue (2 papers, 2011 to 2012). "IFN-γ production upon infection is controlled by concomitant production of IL-12 and IL-18 and the IFN-γ-dependent mechanisms associated to resistance to dengue disease involve NOS2 up-regulation and consequent NO production." (PMID 22206036, 2011).
encephalitis (2 papers, 2013). An acute inflammatory process affecting the brain parenchyma. "The delayed death phenotype of Gbp1−/− mice is reminiscent of type II infection in Nos2−/− mice, which succumb due to encephalitis." (PMID 23633952, 2013).
eosinophilia (2 papers, 2008 to 2024). "An unexpected finding was that administration of OVA resulted in decreased ENO in NOS-2-/- mice, previously measured to be high when naive, coupled with the lack of cell recruitment and eosinophilia." (PMID 18505586, 2008). "There is some precedent for these responses, reported as decreased nitrite and nitrate, and a lack of eosinophilia in BAL fluid of NOS-2-/- mice with allergic airway inflammation, as compared to C57Bl6 mice." (PMID 18505586, 2008).
epilepsy (2 papers, 2016 to 2019). A brain disorder characterized by episodes of abnormally increased neuronal discharge resulting in transient episodes of sensory or motor neurological dysfunction, or psychic dysfunction. "The human NOS2 gene (inducible nitric oxide synthase 2) contains an SNP marker of resistance to malaria and epilepsy where the –51 T → C substitution (relative to the transcription start site of this gene) causes NOS2 overexpression." (PMID 28105927, 2016).
fungal infection (2 papers, 2011 to 2015). "The analysis of the M1/M2 (NOS2/ARG1 and SOCS3/SOCS1) ratios expressed by A/J and B10.A cells demonstrates that curdlan increases but laminarin decreases the M1/M2 ratios of A/J macrophages induced by fungal infection." (PMID 26388856, 2015).